NLRP1 (NLR family pyrin domain containing 1)
Diseases named in the same sentence as NLRP1 in open-access papers (continued):
Sharing a sentence is not in itself a finding about the gene and the disease.
melanoma (continued). "Moreover, the lack of NLRP1 leads to reduced activity of caspase-1, IL-1β, and NF-κB in various human melanoma cell lines." (PMID 33015196, 2020). "Additionally, our current work on the involvement of NLRP1 inflammasome in acquired drug resistance could help tailor melanoma treatment with non-chemotherapy options, such as targeted therapies." (PMID 32899791, 2020). "For example, CASP4, NLRP1, MEFV, IL18, and NINJ1 correlated positively with GSDMD in metastatic melanoma patients but not in primary melanoma patients." (PMID 38229080, 2024). "The fundamental constituent of inflammasomes, comprising pyrin, the NOD-like receptor (NLR) family (NLRP1, NLRP3, NLRP6, NLRP9, and NLRC4), and absent in melanoma 2 (AIM2)." (PMID 39125817, 2024). "To date, there are five typical inflammasome sensors, including NOD-like receptor (NLR) family pyrin domain-containing 1 (NLRP1), NLRP3, NLR family caspase recruitment domain-containing 4, absent in melanoma 2, and Pyrin." (PMID 34922574, 2021). "To date, various inflammasomes, including NLRP1, NLRP2, NLRP3, absent in melanoma (AIM2) and NLRC4, have been identified." (PMID 31941010, 2020). "Of note, additional studies have indicated that not only NLRP3, but also NLRP1, NLRC4 [NLR (Nod-like receptor) family CARD-containing 4] and AIM2 (absent in melanoma 2) form the inflammasomes that drive inflammation in response to a wide variety of molecular patterns." (PMID 22701621, 2012). "Moreover, a nucleotide-binding oligomerization domain-like receptor (NLR) protein is the main component of inflammasomes and is classified into four types: NLRP1/NALP1b inflammasome, NLRC4/IPAF inflammasome, NLRP3/NALP3 inflammasome, and AIM2 (absent in melanoma 2) containing inflammasome." (PMID 34067673, 2021).
autoimmune disease (29 papers, 2012 to 2025). A disorder resulting from loss of function or tissue destruction of an organ or multiple organs, arising from humoral or cellular immune responses of the individual to their own tissue constituents. "Specific polymorphisms in the NLRP1 gene leading to its constitutive activation are associated with an elevated risk of autoimmune disorders such as vitiligo and rheumatoid arthritis." (PMID 39143032, 2024). "NLRP1 mutations in both coding and non-coding regions are implicated in various diseases, including metabolic disorders, cancer, and autoimmune diseases." (PMID 39143032, 2024). "Second, several recent studies have implicated a role for the NLRP1 mutations in multiple autoimmune diseases, suggesting the pathogenic mechanisms of many disease-causing mutations." (PMID 36426349, 2022). "A novel autoimmune disease, NLRP1-associated autoinflammation with arthritis and dyskeratosis (NAIAD) was described in 2017 with NRLP1 as the implicated pathogenic factor." (PMID 32878648, 2020). "Many studies have shown that NLRP1 polymorphisms are implicated in several autoimmune diseases, including rheumatoid arthritis, systemic sclerosis, Crohn's disease, Addison's disease, and vitiligo-associated multiple autoimmune diseases." (PMID 31396539, 2019). "Genetic variants in NLRP1 have been reported to correlate to various autoimmune diseases." (PMID 31396539, 2019). "In sum, we identified a potential genetic relationship in the Caucasian population between the NLRP1 rs12150220 polymorphism and a decreased susceptibility to autoimmune diseases, especially autoimmune Addison's disease, type 1 diabetes, or systemic lupus erythematosus." (PMID 29152150, 2017). "Moreover, as discussed later, polymorphisms of NLRP1 have been linked to an increased risk developing a number of autoimmune diseases." (PMID 24367371, 2013). "Interestingly, NLRP1 a common autoimmune disease risk factor has been reported to be associated with the ATA and lung fibrosis-positive subgroups of SSc patients." (PMID 22531499, 2012). "NLRP1 plays an important role in cellular inflammation, apoptosis, cell death, and autoimmune diseases." (PMID 37214347, 2023). "The nucleotide-binding oligomerization domain (NOD)-like receptor protein 1 (NLRP1) plays an important role in the cellular inflammatory response, cell apoptosis, cell death, and autoimmune diseases." (PMID 37214347, 2023). "NLR family, pyrin domain containing 1 (NLRP1) gene on chromosome 17p13 is involved in the primary immune system and was shown to be associated with generalized vitiligo and other autoimmune diseases." (PMID 25097674, 2014). "Additional immune-regulatory loci include MICA/MICB, CTLA4, PTPN22, CIITA, CLEC16A, CD274 (PD-L1), and NLRP1 (NALP1)—variants shared with other autoimmune diseases, underscoring common immune checkpoints rather than AAD-specific genes." (PMID 41465179, 2025). "As for the differences with other autoimmune diseases, the expression of NLRP1 varies widely in distinct tissues and the effect of SNP could be cell specific." (PMID 31396539, 2019). "As one of the best characterized inflammasome-forming NLR family members, NLRP1 (NLR family pyrin domain containing 1) inflammasome is considered to be a reasonable and effective target for modulating the initiation and progression of various autoimmune disorders." (PMID 31396539, 2019). "Meanwhile, it was reported that NLRP1/IL-1β polymorphism was correlated with the pathogenesis of autoimmune diseases including lupus; however, exact evidence about how NLRP1 was involved in lupus was not illustrated." (PMID 31427885, 2019). "NLRP1 protein is a member of the nucleotide oligomerization domain-like receptors (NLRs) family and regulates inflammasome activation, cellular apoptosis, innate immune system, and some inflammatory disorders or autoimmune diseases." (PMID 29152150, 2017).
autoimmune disease (continued). "A genetic study of families with vitiligo with or without other autoimmune diseases has revealed a link between these autoimmune disorders and the presence of polymorphisms in NLRP1 gene." (PMID 28191008, 2017). "As recent studies suggested the important role of NALP1 and NALP3 genes in the predisposition to autoimmune disorders, we evaluated the possible association of single nucleotide polymorphisms (SNPs) in NLRP1 and NLRP3 genes in celiac patients and in healthy individuals." (PMID 23658628, 2013). "Because the serum NLRP1 level may change due to the patients suffering from certain inflammatory diseases, autoimmune diseases, blood diseases, malignant tumors, liver and kidney dysfunction, and other diseases, this experiment has not been included in this population." (PMID 37214347, 2023). "NLRP1 and NLRP3 inflammasomes are the best characterized and they have been related to several autoimmune diseases." (PMID 35457026, 2022).
Alzheimer disease (24 papers, 2013 to 2026). A progressive, neurodegenerative disease characterized by loss of function and death of nerve cells in several areas of the brain leading to loss of cognitive function such as memory and language. "Increasing evidence has shown that the NOD-like receptor protein 1 (NLRP1) inflammasome is associated with Aβ generation and deposition, which contributes to neuronal damage and neuronal-inflammation in Alzheimer's disease (AD)." (PMID 37055801, 2023). "Polymorphisms in the NLRP1 gene are associated with Alzheimer’s disease and multiple sclerosis, the latter resulting in an increase of IL-1β expression in peripheral blood mononuclear cells isolated from patients carrying these polymorphisms." (PMID 31892810, 2019). "Also, knockdown of NLRP1 or caspase-1 reduced neuronal loss in animal models of temporal lobe epilepsy and Alzheimer’s disease." (PMID 31127201, 2020). "NLRP3 is the most studied one and the one that seems to be most related to pyroptosis in Alzheimer’s disease, but other inflammasomes have also been reported to contribute to the disease, such as NLRP1." (PMID 40002308, 2025). "NLRP1 inhibition improves outcomes in Alzheimer’s disease, traumatic brain injury, ischemic stroke and SAH animal models." (PMID 41353157, 2025). "The most highly cited reference is “The NLRP3 and NLRP1 inflammasomes are activated in Alzheimer’s disease,” published in Molecular Neurodegeneration with Marina Saresella as the first author." (PMID 40538660, 2025). "A previous study showed that silencing NLRP1 inflammasome reduced neuronal cell pyroptosis in a mouse model of Alzheimer’s disease." (PMID 37143681, 2023). "In Alzheimer's disease (AD), β‐amyloid deposition can activate NLRP1 inflammasome, mediate the occurrence of pyroptosis and trigger local inflammation." (PMID 34632701, 2021). "There is also evidence linking NLRP1 to longevity, Alzheimer disease, and CVD, suggesting it interacts with other lipid related-genes." (PMID 24917880, 2014). "Moreover, increased NLRP1 expression was measured in monocytes isolated from Alzheimer’s disease patients upon LPS and amyloid beta stimulation." (PMID 31892810, 2019). "SGD exerts neuroprotective and cognitive improvement effects by reducing NLRP1 and NLRP3 in Alzheimer’s disease cell and mouse models." (PMID 41190029, 2025). "In another research on Alzheimer’s Disease (AD), schisandrin (SCH) was proven to improve in AD mice cognitive impairment by inhibiting neural pyroptosis and apoptosis induced by the NLRP1 inflammasome, even though the profound mechanism is unknown." (PMID 39940319, 2025). "In Alzheimer’s disease, accumulation of fibrillar peptide amyloid-β after phagocytosis releases cathepsin B that is sensed by NLRP3 (and at a lesser extent NLRP1) and induces activation of NLRP1 and 3 inflammasomes, which in turn have been found to worsen Alzheimer’s disease patient conditions." (PMID 38644450, 2024). "As the first identified inflammasome, NLRP1 inflammasome has been reported to involve in the pathological processes of many nervous system diseases such as spinal cord injury (SCI), traumatic brain injury (TBI), Alzheimer’s disease (AD), and nociception." (PMID 29776417, 2018). "Neuroinflammation mediated by NLRP1 (nucleotide-binding oligomerization domain (NOD)-like receptor protein 1) inflammasome plays an important role in many neurological diseases such as Parkinson’s disease (PD) and Alzheimer’s disease (AD)." (PMID 28732502, 2017).
psoriasis (24 papers, 2017 to 2026). An autoimmune condition characterized by red, well-delineated plaques with silvery scales that are usually on the extensor surfaces and scalp. "Variations in NLRP1 are associated with susceptibility to inflammation and autoimmunity contributing to vitiligo, psoriasis and AD." (PMID 35929827, 2022). "In this same study, NLRP1 SNPs were found to have no significant relation to psoriasis, though in another study in a Swedish cohort, NLRP1 SNPs were linked to psoriasis susceptibility." (PMID 33925158, 2021). "Another important finding that confirmed the significant correlation between NLRP1 gene polymorphisms and psoriasis is the demonstration that homozygosity for the rs878329C allele was also correlated with the onset of psoriasis at an earlier age." (PMID 34072753, 2021). "This is further supported by the identification of single nucleotide polymorphisms in NLRP1, which pre-disposes to skin disorders like psoriasis and vitiligo." (PMID 29348630, 2018). "Finally, we discovered endogenous cytoplasmic double stranded (ds) RNA, recently associated with cellular perturbations in psoriasis, as a novel NLRP1 activator." (PMID 42215430, 2026). "Polymorphisms in NLRP3 and CARD8 are associated with increased risk of psoriasis development, while NLRP1 mutations have been associated with diverse cutaneous inflammatory diseases, including psoriasis, highlighting the critical role of NLRP1 in epidermal biology." (PMID 35929827, 2022). "The risk of contracting psoriasis is also associated with variants of the NLRP1 gene." (PMID 32640751, 2020). "Similarly, there is some evidence that NLRP1 rs8079034 also predisposes to psoriasis." (PMID 32528469, 2020). "Our results identify a novel endogenous dsRNA-mediated NLRP1-IL-1-IL-36γ signaling axis relevant in psoriasis and suggest its targeting as a promising treatment strategy." (PMID 42215430, 2026). "The relevance of these findings is reflected by the expression of NLRP1 and inflammasome activation in lesions of psoriasis patients." (PMID 42215430, 2026). "Sharon and Jiquan demonstrated a significant correlation of NLRP1 and NLRP3 gene polymorphism with psoriasis." (PMID 34790822, 2021). "The results of these studies clearly indicate the role of the NLRP1 inflammasome in the development and course of psoriasis." (PMID 34072753, 2021). "The inflammasome sensor proteins NLRP-1 and NLRP-3 are expressed in psoriatic lesions and specific polymorphisms have been associated with psoriasis pathogenesis and susceptibility." (PMID 32903782, 2020). "Data suggest that the mixed pro-inflammatory micro-milieu in Th1/Th17-mediated psoriasis provides a relevant setting for NLRP1-dependent inflammasome activation." (PMID 28422993, 2017). "Here, we investigate regulators and triggers for epidermal NLRP1-dependent caspase-5 activation in a psoriasis-relevant cytokine micro-milieu." (PMID 28422993, 2017). "NLRP1 activation induced histological and molecular features highly reminiscent of psoriasis." (PMID 42215430, 2026). "Along this line, genetic data have also indicated an association with polymorphism in NLRP1, NLRP3, and AIM2 in psoriasis, and more recently, the association with a genetic polymorphism in inflammasome-related genes has been shown in patients with psoriatic arthritis." (PMID 34502368, 2021). "In addition, researchers revealed that the expression level of NLRP1 mRNA and circulating IL-18 is significantly increased in the peripheral blood of patients suffering from psoriasis." (PMID 34072753, 2021). "They reported the overtransmission of the NLRP1 rs878329C and rs8079034C genotypes in psoriasis." (PMID 34072753, 2021). "The authors attributed the described phenomenon to isostearic acid, which is the main component of NLRP1 activation in a murine model, indicating that Aldara might stimulate psoriasis-like phenotypes in different immune pathways, requiring both inflammasome and IMQ induced response." (PMID 34072753, 2021).
psoriasis (continued). "Our observations on an enhanced caspase-5 regulation in the presence of IL-17A and NLRP1 inflammasome activity in keratinocytes suggests a functional contribution for epidermal IL-1β production in psoriasis and likely other diseases, where Th17 may also contribute, such as lupus erythematosus." (PMID 28422993, 2017). "One study revealed that inflammasome sensors, NLRP3, NLRP1, CASP1, and AIM2, enhanced expression in psoriasis patients." (PMID 36110207, 2022). "The databases were searched using the terms “inflammasome”, “NLRP1”, “NLRP3” or “AIM2” and “psoriasis” or “psoriatic arthritis”." (PMID 34072753, 2021). "The study shows that patients with psoriasis have increased plasma levels of IL-1β and IL-18 and increased constitutive expression of the inflammasome sensors NLRP3, NLRP1, and AIM2 in peripheral blood cells, together with increased caspase 1 reactivity." (PMID 34502368, 2021). "In this systemic review, we collect recent and comprehensive evidence from the inflammasomes, NLRP1, NLRP3, and AIM2, in pathogenesis of psoriasis." (PMID 34072753, 2021). "Therefore, NLRP1 and NLRP3 may play roles in the dysregulated innate immune response that is characteristic of psoriasis." (PMID 29850521, 2018). "Patients with psoriasis present relatively high plasma levels of inflammasome-generated IL-1β and high expression of inflammasome components such as NLRP3, NLRP1, and absent in melanoma 2 (AIM2)." (PMID 37964882, 2023). "Furthermore, mRNA of NLRP1, NLRP3, AIM2, PYCARD and CASP1 was observed in both lesional and non-lesional epidermis of psoriasis patients." (PMID 37325658, 2023).
ischemic stroke (20 papers, 2019 to 2025). A stroke disorder caused by obstruction of blood flow to the brain, due to thrombotic (local blood clot formation) or embolic (due to a blood clot or other material traveling from another site) event. "We draw ROC curves to assess the diagnostic value of ASITN/SIR grade and NLRP1 for the prognoses of ischemic stroke patients." (PMID 37000063, 2023). "In our study, we found that serum NLRP1 levels was decreased in ischemic stroke patients with poor prognosis and was associated with other inflammatory factors as well as collateral circulation." (PMID 37000063, 2023). "In brief, our findings suggested that the anti-pyroptosis effect of EE after ischemic stroke was associated with the inhibition of the NF-κB p-65 signaling pathway and the reduced expression levels of NLRP1 and NLRP3 inflammasome-related proteins." (PMID 34646128, 2021). "ASITN/SIR grade and NLRP1 could be potential diagnostic biomarkers of poor prognosis of ischemic stroke patients." (PMID 37000063, 2023). "In ischemic stroke, multiple inflammasomes (NLRC4, NLRP1, NLRP3, NLRP6, AIM2) have been implicated, with AIM2 uniquely recognizing cytosolic dsDNA to drive AIM2-ASC-caspase-1 complex formation and GSDMD-mediated pyroptosis." (PMID 41344159, 2025). "The serum levels of NLRP1 were remarkably enhanced in the ischemic stroke patients compared with the carotid atherosclerosis patients." (PMID 37000063, 2023). "This research aimed to combine serum NLR-pyrin domain containing 1 (NLRP1) levels and collateral circulation to assess ischemic stroke patients and predict the prognoses of the patients." (PMID 37000063, 2023). "In the present prospective observational research, we aimed to combine serum NLRP1 levels and collateral circulation to assess ischemic stroke patients and predict the prognosis of the patients." (PMID 37000063, 2023). "This study showed that the serum NLRP1 levels were remarkably decreased in ischemic stroke patients." (PMID 37000063, 2023). "It was found that NLRP1, ASITN/SIR grade, infarct volume, NIHSS, IL-6, and IL-1β were the risk factors for bad prognosis of ischemic stroke patients." (PMID 37000063, 2023). "To further investigate the relationship between NLRP1 and inflammatory factors in ischemic stroke patients, we measured the serum levels of NLRP1, CRP, IL-6, TNF-α, and IL-1β by ELISA." (PMID 37000063, 2023). "Hitherto, the inflammasomes NLRC4, NLRP1, NLPR3, NLRP6 and AIM have been implicated in ischemic stroke." (PMID 37353794, 2023). "Encouragingly, some miRNAs that had been reported in TBI pathogenesis were included in the ceRNA networks, such as miR-9a-5p, overexpression of miR-9a-5p ameliorates NLRP1 inflammasome-mediated ischemic injury in rats following ischemic stroke." (PMID 36711143, 2022). "In the literature, NLRP3 and NLRP1 represent two members of the family of inflammasomes best investigated, and it is now undisputed the pivotal role they played in the pathogenesis of ischemic stroke." (PMID 36297283, 2022). "For example, ischemic stroke was shown to activate both NLRP1 and NLRP3 inflammasomes in neurons through nuclear factor kappa-light-chain-enhancer of activated B cells (NF-κB)- and mitogen-activated protein kinase-dependent mechanisms." (PMID 33328988, 2020). "Thirdly, the molecular mechanism of NLRP1 affecting ischemic stroke development is unclear." (PMID 37000063, 2023). "Serum NLRP1 levels and clinical data in ischemic stroke patients with different prognosis." (PMID 37000063, 2023). "This study might reveal the clinical significance of NLRP1 in ischemic stroke patients, as well as provide novel research targets for ischemic stroke treatment." (PMID 37000063, 2023). "In view of the contribution of NLRP1 inflammasome to the pathogenesis of ischemic stroke, it could be advantageous designing a therapeutic strategy that inhibits this inflammasome." (PMID 36297283, 2022).